MAP3K2 (mitogen-activated protein kinase kinase kinase 2)
Description:
Component of a protein kinase signal transduction cascade. Regulates the JNK and ERK5 pathways by phosphorylating and activating MAP2K5 and MAP2K7 (By similarity). Plays a role in caveolae kiss-and-run dynamics.
Synonyms: MEKK2; MEKK2B
Tractability: Small molecule: a structure with a bound ligand is known; a high-quality ligand is known; it belongs to a druggable protein family. PROTAC: UniProt records ubiquitination sites on it; ubiquitination databases record sites on it; its protein half-life has been measured; a small molecule that binds it is known.
Target class: Enzyme; STE protein kinase STE11 family; Kinase; Protein Kinase; STE protein kinase MEKK2; STE protein kinase group
Safety:
Unwanted effects reported when the protein is acted on. In parentheses: how it was acted on, where the effect was seen, and who reports it.
cardiac arrhythmia (cardiovascular system; source: Lamore et al. (2017))
Gene: Protein-coding gene on chromosome 2 (127,298,668 to 127,388,465, reverse strand). Ensembl gene ENSG00000169967.
Subcellular location: Cytoplasm; Nucleus
Subcellular location (Human Protein Atlas): Cytosol; Nucleoplasm
Gene Ontology:
Molecular function: protein binding; protein kinase activity; protein kinase binding; protein serine/threonine kinase activity; ATP binding; MAP kinase kinase kinase activity; protein serine kinase activity
Biological process: cellular response to mechanical stimulus; intracellular signal transduction; MAPK cascade
Cellular component: cytosol; nucleoplasm; cytoplasm; nucleus
Genetic constraint (gnomAD): Loss-of-function variants: 9 observed, 26.19 expected, observed/expected ratio (o/e) 0.34, 90% interval 0.21 to 0.6. The upper end of that interval is the gene's LOEUF score, 0.6, which puts it in group 2 of 6, group 1 being the genes least tolerant of losing a copy. Missense variants: 312 observed, 368.62 expected, observed/expected ratio (o/e) 0.85, 90% interval 0.77 to 0.93. Synonymous variants: 130 observed, 126.35 expected, observed/expected ratio (o/e) 1.03, 90% interval 0.89 to 1.19.
Homologues: Orthologues: chimpanzee MAP3K2 (99% identical), macaque MAP3K2 (99% identical), dog MAP3K2 (99% identical), pig MAP3K2 (99% identical), rabbit MAP3K2 (98% identical), mouse Map3k2 (96% identical), rat Map3k2 (96% identical), guinea pig MAP3K2 (93% identical), tropical clawed frog map3k2 (87% identical), zebrafish map3k2 (82% identical), Caenorhabditis elegans sek-5 (13% identical), Caenorhabditis elegans sek-4 (13% identical), and 2 more. Paralogues in human: MAP3K3 (66% identical), MAP3K4 (31% identical), NEK1 (17% identical), MAP2K5 (16% identical), MAP2K1 (15% identical), MAP2K7 (15% identical), MAP2K2 (15% identical), MAP2K4 (14% identical).
Diseases named in the same sentence as MAP3K2 in open-access papers:
MAP3K2 is named in the same sentence as 65 diseases in open-access papers, as found by Europe PMC text mining. Sharing a sentence is not in itself a finding about the gene and the disease. The quoted sentences say what the papers report.
breast carcinoma (10 papers, 2015 to 2025). "For example, MAP3K2 overexpression has been shown to reverse the miR‐335‐mediated inhibition of breast cancer cell proliferation." (PMID 40035259, 2025). "Only 0.5% of the total transcriptome correlated with the presence of Tregs and only four transcripts, BIRC6, MAP3K2, USP4 and SMG1, were commonly shared among the different breast cancer subtypes." (PMID 38710724, 2024). "We next correlated the expression of commonly shared identified genes; BIRC6, MAP3K2, USP4 and SMG1 with immune populations in different breast cancer subtypes." (PMID 38710724, 2024).
hepatocellular carcinoma (9 papers, 2012 to 2025). A malignant tumor that arises from hepatocytes. "CircBACH1 expression is elevated in both HCC tissues and HBV-transfected hepatocellular carcinoma cells, where it regulates HBV replication and hepatocellular carcinoma progression via the miR-200a-3p/MAP3K2 pathway." (PMID 37819576, 2023). "In conclusion, miR-302a inhibited proliferation and promoted apoptosis in human hepatoma cells by targeting MAP3K2 and PBX3." (PMID 30765768, 2019). "Likewise, miR-106a-5 regulates oxidative stress-induced intestinal barrier damage by targeting MAP3K2 in prelaying ducks, and miR-93-5p promotes hepatocellular carcinoma progression by directly targeting MAP3K2 within the JNK/p38 signaling pathway." (PMID 41425567, 2025). "Moreover, miR-93-5p in hepatocellular carcinoma has been proven to bind to the 3′-untranslated region (UTR) of mitogen-activated protein kinase kinase kinase 2 (MAP3K2)." (PMID 34198846, 2021). "Subsequent research also confirmed that both miR-302 and miR-299-3p bind to the complementary sequences of the MAP3K2-3′-UTR, and thereby inhibit cell proliferation by downregulating MAP3K2 in HepG2/SMMC-7721 hepatocellular carcinoma and lung squamous cell carcinoma, respectively." (PMID 35432472, 2022).
lung cancer (7 papers, 2017 to 2022). A malignant neoplasm involving the lung. "While knockdown of MAP3K2 by siRNA inhibited lung cancer cell proliferation, migration and invasion in vitro." (PMID 35432472, 2022). "In line with our data, MAP3K2 was reported to be an oncogene in nonsmall cell lung cancer and triple-negative breast cancer." (PMID 34335755, 2021). "Knockdown of MAP3K2 using RNA interference inhibited the growth of hepatocarcinoma cells and lung cancer cells, whereas knockdown of MAP3K2 promoted the proliferation of HeLa cells." (PMID 29158522, 2017). "In lung cancer tissues, higher expressed MAP3K2 was confirmed." (PMID 35432472, 2022). "In lung cancers and PCs, SMYD3 has a pivotal role in the regulation of oncogenic RAS signaling through the methylation of MAP3K2 kinase on lysine 206, which induces MAP3K2 release from the negative regulator PP2A phosphatase complex and therefore promotes ERK1/2 phosphoactivation." (PMID 34503239, 2021). "However, in lung cancer and pancreatic cancer, SMYD3 is localized in the cytoplasm and activates the ERK pathway by methylating MAP3K2.7, 11-13 Although SMYD3 is tightly connected to carcinogenesis, there are few articles about the role of SMYD3 in ovarian cancer." (PMID 31417652, 2019).
glioblastoma (6 papers, 2017 to 2023). The most malignant astrocytic tumor (WHO grade IV). "CircPITX1 facilitated glioblastoma evolvement via acting as a competing endogenous RNA to regulate MAP3K2 by absorbing miR-379-5p." (PMID 32190004, 2020). "In addition, circPITX1 promotes glioblastoma evolution by regulating MAP3K2 as a competitive endogenous RNA through the uptake of miR-379-5p." (PMID 36358938, 2022). "However, in glioblastoma cells, MAP3K2 acts as a tumour suppressor and promotes apoptosis." (PMID 29158522, 2017). "Their data showed that miR-93 was downregulated in human glioblastoma cell lines, and restoration of miR-93 levels in glioblastoma cells led to a decreased expression of an array of inflammatory genes (HIF-1α, MAP3K2, IL-6, G-CSF, IL-8, LIF, and IL-1β)." (PMID 38239396, 2023).
non-small cell lung carcinoma (5 papers, 2018 to 2024). A group of at least three distinct histological types of lung cancer, including non-small cell squamous cell carcinoma, adenocarcinoma, and large cell carcinoma. "A previous study showed that miR-186 suppressed cell proliferation and metastasis by targeting MAP3K2 in a case of non-small-cell lung cancer." (PMID 33628370, 2021). "Furthermore, miR-186 can suppress cell proliferation and metastasis through targeting MAP3K2 in non-small cell lung cancer." (PMID 35432472, 2022). "KIAA1429 can promote the resistance to gefitinib, an EGFR (epidermal growth factor receptor) inhibitor, by increasing MAP3K2 (mitogen-activated protein kinase kinase kinase 2) expression in lung adenocarcinoma, or by suppressing autophagy mediated by WTAP in non-small cell lung cancer." (PMID 39456252, 2024).
acute myocardial infarction (4 papers, 2022 to 2024). Necrosis of the myocardium, as a result of interruption of the blood supply to the area. "Map3k2 is targeted by miR-335 to reduce myocardial damage, consequently helping to attenuate myocardial infarction." (PMID 35707845, 2022). "Notably, studies have also demonstrated that the levels of MAP3K2 in serum samples from patients with acute myocardial infarction are elevated." (PMID 38612276, 2024). "The overexpressed BMSC-derived exosomal miR-338 can prevent cardiomyocyte apoptosis by regulating the mitogen-activated protein kinase kinase kinase 2(MAP3K2)/c-Jun N-terminal kinase (JNK) signaling pathway and significantly repair cardiac function in a rat model of myocardial infarction." (PMID 39350967, 2024).
colitis (4 papers, 2021 to 2025). Inflammation of the colon. "Map3k2-deficient mice are more susceptible to DSS-induced colitis compared with wild type controls, further emphasizing a protective role of MRISCs against inflammation of the colon." (PMID 34512636, 2021). "In contrast, the Col1a2-creERT2; Map3k2fl/fl mice (Map3k2 is specifically ablated in the subepithelial stromal cells) developed a severe colitis phenotype similar to the Map3k2−/− mice." (PMID 34080092, 2021). "They observed that Map3k2−/− mice exhibited an enhanced colitis phenotype, with a significantly reduced number of colonic stem cells present following exposure to dextran sulfate sodium (DSS)." (PMID 34080092, 2021). "Vil1-cre; Map3k2fl/fl mice—wherein Map3k2 is specifically ablated in epithelial cells—developed a similar degree of DSS-induced colitis as control mice." (PMID 34080092, 2021). "Therefore, the observed protective effect (i.e., antagonizing of DSS-induced colitis) results from Map3k2 in stromal cells." (PMID 34080092, 2021). "Interestingly, recent study showed that Map3k2-regulated intestinal stromal cells (MRISCs) residing around the crypt base enhance production of R-Spo1 in response to dextran sodium sulfate (DSS)-induced colitis and protect colonic ISCs." (PMID 34512636, 2021). "Research has demonstrated that mitogen-activated protein kinase kinase 2 (MAP3K2) is essential for CD4 + T cell-mediated inflammation in the intestine, and Th1 cells regulate colitis severity through MAP3K2." (PMID 41257990, 2025). "MAP3K2, a member of the MAP3K family, plays a pivotal role in the IL-18/MAP3K2/JNK pathway, which is essential for T-cell immunity in the intestine and shows promise as a new target for intervention in T-cell-mediated colitis." (PMID 38612276, 2024).
colon cancer (4 papers, 2022 to 2025). "In this study, we observed that miR-372-3p is less strongly expressed in patients with colon cancer, and this pattern was associated with highly expressed MAP3K2 involved in the regulation of MAP kinases and other signaling pathways." (PMID 35432472, 2022). "Further analysis of the expression of 22 colon cancer samples showed significant (>2-fold increased) up-regulation of MAP3K2 in 77.3% (17/22) of patients, while there was an increase (>2-fold decrease) in 27.3% (6/22) of adjacent tissue samples." (PMID 35432472, 2022). "In our experiments, a significant increase in MAP3K2 expression was observed in colon cancer tissues compared to matched normal tissues (***p < 0.0001)." (PMID 35432472, 2022). "The target relationship between miR-372-3p and MAP3K2 was verified using luciferase assays in SW480 colon cancer cells." (PMID 35432472, 2022). "To validate the predicted MAP3K2 that was actually suppressed by miR-372-3p in colon cancer cells, we constructed two luciferase reporter plasmids containing the miR-372-3p target sites (264–270 and 6552–6558) in the MAP3K2 3′-UTR region." (PMID 35432472, 2022). "In colon cancer, miR‐372‐3p targets MAP3K2, thereby suppressing tumor development." (PMID 40035259, 2025). "Overall, the results obtained herein suggest that miR-372-3p may function as a tumor-suppressor miRNA in colon cancer by targeting MAP3K2." (PMID 35432472, 2022). "In our experiments, the higher expression of MAP3K2 in patients with colon cancer was negatively correlated with the miR-372-3p expression, indicating that MAP3K2 may be a potential target of miR-372-3p." (PMID 35432472, 2022). "We found that miR-372-3p mimics inhibit the cell viability and clone-formation ability in SW480 colon cancer cells, and this effect may result from the targeted inhibition of mitogen-activated protein kinase kinase kinase 2 (MAP3K2, MEKK2) expression." (PMID 35432472, 2022).
gastric cancer (4 papers, 2021 to 2025). A primary or metastatic malignant neoplasm involving the stomach. "In gastric cancer, NR2F1-AS1 enhances cell growth through various axes, including miR-29a/VAMP7, miR-190a/PHLDB2/AKT3, SPI1/ST8SIA1, and miR-493-5p/MAP3K2." (PMID 40828427, 2025). "Previous studies have demonstrated that lncRNA NR2F1-AS1 can influence breast and gastric cancer progression by activating insulin-like growth factor-1 (IGF-1)/IGF-1R/ERK, MAP3K2, and AKT3, which crosstalk with AKT." (PMID 35283481, 2022). "In gastric cancer, NR2F1-AS1 acts as an EMT-inducing lncRNA that enhances cell motility via the miR-29a/VAMP7 axis, activation of AKT3 through miR-190a/PHLDB2, SPI1-mediated transcriptional upregulation of ST8SIA1, and miR-493-5p/MAP3K2 signaling." (PMID 40828427, 2025).
liver cancer (4 papers, 2012 to 2025). An epithelial or non-epithelial malignant neoplasm that arises from the liver. "The results showed that liver cancer cell lines exhibited low miR-302a expression and MAP3K2 and PBX3 were confirmed to be the target genes of miR-302a." (PMID 30765768, 2019). "In this study, the expression of miR-302a and MAP3K2/PBX3 were evaluated by qPCR in liver cancer cell lines." (PMID 30765768, 2019). "Previous experiments have demonstrated that circBACH1 promotes HBV replication and liver cancer development by regulating the miR-200a-3p/mitogen-activated protein kinase kinase kinase 2 (MAP3K2) axis, while circ-ARL3 enhances HBV replication by sponging miR-1305." (PMID 40182764, 2025). "And miR-302a, MAP3K2 and PBX3 expression levels were detected in liver cancer cells and tissues." (PMID 30765768, 2019). "Moreover, miR-520b targeting mitogen-activated protein kinase kinase kinase 2 (MEKK2) and cyclinD1 inhibits the proliferation of liver cancer cells." (PMID 24886421, 2014).
glioma (3 papers, 2013 to 2023). A benign or malignant brain and spinal cord tumor that arises from glial cells (astrocytes, oligodendrocytes, ependymal cells). "Through literature research, we screened out five mRNAs (SPARC, YY1, ERBB4, MAP3K2, and FZD6) that are highly expressed in glioma tumor tissues and promote glioma progression." (PMID 37554539, 2023). "For example, miR-26a that is upregulated in glioma tissues suppresses PTEN, RB1 and MAP3K2/MEKK2 expression and inhibits c-JUNN-terminal kinase-dependent apoptosis." (PMID 24202447, 2013). "Recently, four groups reported different circPITX1-mediated ceRNETs in glioma cells, i.e., circPITX1/miR-518a-5p/IL17RD, circPITX1/miR-1304/ERBB4, circPITX1/miR-379-5p/mitogen-activated protein kinase 2 (MAP3K2), and circPITX1/miR-329-3p/NIMA-related kinase 2 (NEK2)." (PMID 33995499, 2021).
lung adenocarcinoma (3 papers, 2022 to 2024). A carcinoma that arises from the lung and is characterized by the presence of malignant glandular epithelial cells. "In previous work, we identified a specific mechanism in which the SMYD3-mediated methylation of MAP3K2 potentiates the oncogenic KRAS-driven pathway in lung adenocarcinomas." (PMID 35819319, 2022). "We previously identified an oncogenic activity of SMYD3 mediated by MAP3K2 methylation, promoting KRAS-driven lung adenocarcinoma tumorigenesis through ERK1/2 oncogenic activation." (PMID 35819319, 2022).
lung squamous cell carcinoma (3 papers, 2020 to 2024). "In lung squamous cell carcinoma, it promotes proliferation, migration, and tumor progression by modulating the expression of Bcl-2 and Bax, enhancing ITGB8 expression, and binding to miR-299-3p, resulting in elevated MAP3K2 expression." (PMID 38612418, 2024).
melanoma (3 papers, 2021 to 2022). A malignant, usually aggressive tumor composed of atypical, neoplastic melanocytes. "Forkhead box D3-Antisense RNA 1 (FOXD3-AS1), instead, seems to promote proliferation, invasion and migration in melanoma cell lines through the miR-325/MAP3K2 axis." (PMID 33503876, 2021). "Moreover, it was found that FOXD3-AS1 enhanced cell apoptosis of melanoma A375, SK-MEL-1 and SK-MEL-2 cells through either the miR-325/MAP3K2 axis or the miR-127-3p/FJX1 axis." (PMID 35280790, 2022). "Although both genes have not been extensively studied in melanoma so far, MAP3K2 participates in regulation of several pathways such as MAPK signaling, β-catenin pathway and Hedgehog (Hh) pathway in medulloblastoma and osteoblasts, and FJX1 promotes angiogenesis in colorectal carcinoma." (PMID 34638331, 2021). "lncRNA forkhead box D3 antisense RNA 1 (FOXD3-AS1) is overexpressed in melanoma and functions as oncogene by sponging miR-127-3p and miR-325 and upregulating their target genes four-jointed box kinase 1 (FJX1) and mitogen-activated protein kinase kinase kinase 2 (MAP3K2), respectively." (PMID 34638331, 2021). "Hence, interfering with MAP3K2 activation by modulating FOXD3-AS1 could revert proliferation, invasion and migration of melanoma cells." (PMID 33503876, 2021).
pancreatic cancers (3 papers, 2019 to 2023). "In lung and pancreatic cancers, SMYD3 is localized in the cytoplasm, where it enhances RAS/ERK signaling by mediating the methylation of MAP3K2 kinase and preventing its interaction with the PP2A phosphatase complex." (PMID 37237385, 2023).
triple-negative breast carcinoma (3 papers, 2021 to 2023). An invasive breast carcinoma which is negative for expression of estrogen receptor (ER), progesterone receptor (PR), and human epidermal growth factor receptor 2 (HER2). "MAP3K2 has also specifically been demonstrated to regulate the abundance of vimentin in some cancers, such as in triple-negative breast cancer." (PMID 37976356, 2023). "Undoubtedly, miRNA function is cell-type dependent, therefore, miR-34c may function as a tumor suppressor in triple-negative breast cancer (TNBC), and regulates TNBC invasiveness via the MAP3K2 pathway." (PMID 37175874, 2023).
endometriosis (2 papers, 2022 to 2025). The growth of functional endometrial tissue in anatomic sites outside the uterine body. "Hence, miR-340-5p influences the progression of endometriosis by regulating MAP3K2-mediated MAPK/ERK signaling." (PMID 35415247, 2022).
ischemic stroke (2 papers, 2022 to 2023). A stroke disorder caused by obstruction of blood flow to the brain, due to thrombotic (local blood clot formation) or embolic (due to a blood clot or other material traveling from another site) event. "In this study, we showed that miR-152-3p suppressed Bend. apoptosis to attenuate BBB disruption through the MAP3K2/JNK/c-Jun pathway after ischemic stroke." (PMID 36445489, 2023). "Lastly, in accordance with our findings, miR-379-5p was downregulated in patients with ischemic stroke, while its neuroprotective roles in targeting MAP3K2 and JNK/c-Jun signaling to attenuate neuronal autophagy were also reported recently." (PMID 35328807, 2022). "Our data suggested that the miR-152-3p/MAP3K2 pathway might be a potential therapeutic target for ischemic stroke." (PMID 36445489, 2023).
neuroblastoma (2 papers, 2021). Neuroblastoma (NB) is the most common solid, extracranial childhood tumor. "Previous studies have found that HCP5 was shown to regulate neuroblastoma cells activation and promoted neuroblastoma progression by acting as ceRNA to bind with miR-186-5p and regulate MAP3K2 expression." (PMID 34907261, 2021).
prostate tumors (2 papers, 2020 to 2023). "The MAP3K2 gene in the MAPK pathway, which was regulated by the miRNA markers in PRAD, was previously reported to be associated with the growth and metastasis of prostate tumors." (PMID 32523951, 2020).